RARB (retinoic acid receptor beta)
Description:
Receptor for retinoic acid. Retinoic acid receptors bind as heterodimers to their target response elements in response to their ligands, all-trans or 9-cis retinoic acid, and regulate gene expression in various biological processes. The RXR/RAR heterodimers bind to the retinoic acid response elements (RARE) composed of tandem 5'-AGGTCA-3' sites known as DR1-DR5. In the absence or presence of hormone ligand, acts mainly as an activator of gene expression due to weak binding to corepressors. The RXRA/RARB heterodimer can act as a repressor on the DR1 element and as an activator on the DR5 element. In concert with RARG, required for skeletal growth, matrix homeostasis and growth plate function (By similarity).
Synonyms: RAR-beta; HAP; NR1B2; RRB2; RARbeta; MCOPS12; RARbeta1
Tractability: Small molecule: an approved drug acts on it; a structure with a bound ligand is known; a high-quality ligand is known; it belongs to a druggable protein family. PROTAC: it is named in the literature on targeted protein degradation; a small molecule that binds it is known.
Target class: Nuclear receptor; Nuclear hormone receptor subfamily 1 group B member 2; Transcription factor; Nuclear hormone receptor subfamily 1; Nuclear hormone receptor subfamily 1 group B
Chemical probes: PD081566, PD083086
Gene: Protein-coding gene on chromosome 3 (24,687,887 to 25,597,932, forward strand). Ensembl gene ENSG00000077092.
Subcellular location: Nucleus; Cytoplasm; Nucleus (Isoform Beta-1); Nucleus (Isoform Beta-2); Cytoplasm (Isoform Beta-4)
Subcellular location (Human Protein Atlas): Nucleoplasm
Pathways (Reactome):
Developmental Biology: Activation of anterior HOX genes in hindbrain development during early embryogenesis
Gene expression (Transcription): Nuclear Receptor transcription pathway
Signal Transduction: Signaling by Retinoic Acid
Gene Ontology:
Molecular function: sequence-specific double-stranded DNA binding; DNA binding; DNA-binding transcription factor activity, RNA polymerase II-specific; nuclear receptor activity; RNA polymerase II cis-regulatory region sequence-specific DNA binding; DNA-binding transcription factor activity; sequence-specific DNA binding; zinc ion binding
Biological process: embryonic digestive tract development; cell differentiation; negative regulation of transcription by RNA polymerase II; positive regulation of transcription by RNA polymerase II; retinoic acid receptor signaling pathway; signal transduction; regulation of DNA-templated transcription
Cellular component: cytoplasm; nucleoplasm; nucleus; chromatin; RNA polymerase II transcription regulator complex
Genetic constraint (gnomAD): Loss-of-function variants: 17 observed, 53.47 expected, observed/expected ratio (o/e) 0.32, 90% interval 0.22 to 0.48. The upper end of that interval is the gene's LOEUF score, 0.48, which puts it in group 2 of 6, group 1 being the genes least tolerant of losing a copy. Missense variants: 369 observed, 574.7 expected, observed/expected ratio (o/e) 0.64, 90% interval 0.59 to 0.7. Synonymous variants: 215 observed, 204.28 expected, observed/expected ratio (o/e) 1.05, 90% interval 0.94 to 1.18.
Gene-disease validity (ClinGen):
ClinGen rates the evidence that RARB causes each of these diseases.
microphthalmia, syndromic 12 (autosomal dominant): Definitive.
Homologues: Orthologues: chimpanzee RARB (100% identical), macaque RARB (100% identical), rabbit RARB (99% identical), guinea pig RARB (99% identical), pig RARB (99% identical), mouse Rarb (98% identical), rat Rarb (89% identical), dog RARB (88% identical), tropical clawed frog rarb (82% identical), Caenorhabditis elegans sex-1 (27% identical), Drosophila melanogaster EcR (24% identical), Caenorhabditis elegans nhr-19 (22% identical), and 182 more. Paralogues in human: RARA (74% identical), RARG (73% identical), RORA (32% identical), RORB (30% identical), RORC (30% identical), NR1D2 (28% identical), THRB (28% identical), PPARA (27% identical), NR1D1 (27% identical), THRA (26% identical), PPARG (26% identical), PPARD (25% identical), and 6 more.
Diseases named in the same sentence as RARB in open-access papers:
RARB is named in the same sentence as 189 diseases in open-access papers, as found by Europe PMC text mining. Sharing a sentence is not in itself a finding about the gene and the disease. The quoted sentences say what the papers report.
breast carcinoma (85 papers, 2004 to 2025). "Recently, it was found that the promoter hypermethylation of the GSTP1 gene, along with the RARB gene, which encodes retinoic acid receptor beta, is associated with breast cancer, older age, and postmenopausal Peruvian patients." (PMID 39125992, 2024). "The combination of the RARB + GSTP1 PMR was associated with breast cancer (OR = 2.81; 95% CI [1.02–8.22]; p = 0.026), controls under 50 years old (p = 0.048), patients older than 50 (p = 0.007), and postmenopausal (p = 0.034)." (PMID 37548362, 2023). "Promoter hypermethylation of RARB + GSTP1 genes is associated with breast cancer, older age, and postmenopausal Peruvian patients." (PMID 37548362, 2023). "Studies have shown that breast cancer specimens reportedly showed a loss of heterozygosity on chromosome 3 at the 3p24 locus, a region which codes for RARβ along with other genes." (PMID 35406744, 2022). "An increased expression of RARβ has been associated with improved breast cancer-specific survival; therefore, interventions which can improve RARβ expression in solid cancers are highly desirable." (PMID 35406744, 2022). "In breast cancer, whereas in the normal breast the pattern of co-expressed genes suggested that MR and RARB shared association with a number of biological processes, many of these connections were lost." (PMID 33148314, 2020). "Concurrently to the work of Houle and co-workers, it was found a loss of RARβ expression also in several breast cancer cell lines." (PMID 32012980, 2020). "Based on this finding, we explored the association between MR and RARB dual positivity and breast cancer survival." (PMID 33148314, 2020). "Retinoic acid treatment of the nontumorigenic, immortalized mammary epithelial cell line, MCF12A and the non-invasive breast cancer cell line T47D induces the association of the RA nuclear receptor RARβ with a methylcytosine dioxygenase (TET2)." (PMID 31590252, 2019). "Loss of miR-10a and RARβ expression are associated with breast cancer since they are related to tumor suppressor in breast tissue specimens." (PMID 29077020, 2017). "It is believed that changes in RARβ expression underlie neoplastic transformation, and inactivation of RARβ was demonstrated in lung, head and neck, as well as in mammary tumors." (PMID 27011326, 2016). "THRα, which is known to dimerize with RARβ, has also previously been implicated to have a potential tumour suppressor role in breast cancer tissues, confirmed using western blot analysis." (PMID 25934412, 2015). "The purpose of our study was to investigate the effects of RA on human breast cancer cells migration, underlying molecular mechanisms involved and the possible roles of RARβ." (PMID 24720764, 2014). "Both RARα and RARβ have been implicated in the anti-proliferative effects of retinoids against breast cancer." (PMID 20696059, 2010). "Noticeably, RARβ expression distinguishes the tumor associated stroma from the adjacent normal stroma in laser-dissected stromal cells obtained from a small cohort of breast cancer patients." (PMID 38360674, 2024). "Association of the PMR of GSTP1 and RARB genes and the risk of breast cancer." (PMID 37548362, 2023). "Furthermore, the association of qualitative PMR of both genes (RARB + GSTP1) with breast cancer was estimated." (PMID 37548362, 2023). "An increased expression of RARβ has been associated with improved breast cancer-specific survival." (PMID 35406744, 2022). "Finally, the suppressive effect of MR and RAR signalling in breast cancer is supported by the observation that tumours expressing high MR and RARB are associated with better survival outcome." (PMID 33148314, 2020). "We observed a divergence in the biological processes that were overrepresented in the sets of processes associated with MR or RARB co-expressed genes, although both receptors were co-expressed with genes involved in biological processes important to breast cancer biology." (PMID 33148314, 2020).
breast carcinoma (continued). "Moreover, high expression of both MR and RARB was associated with improved breast cancer-specific survival." (PMID 33148314, 2020). "Moreover, they located the RARE in the 3’ of the HOXA5 gene, and found that in the MCF10A, ATRA resistant breast cancer cell line, the loss of both RARβ and HOXA5 expression occurred during the neoplastic transformation." (PMID 32012980, 2020). "Growth inhibition of breast cancer cells by RA has been associated with the induction of RARβ, which may act as a tumour suppressor and appears to be down-regulated in breast cancer cells and, conversely, up-regulated in normal mammary epithelial cells." (PMID 24720764, 2014). "Thus, interactions between MR, RARβ and ER may contribute to the positive association observed between higher MR and RARB and breast cancer disease-specific survival and the suppression of E2-mediated growth stimulation." (PMID 33148314, 2020). "Given that several studies have shown that marker protein E-cadherin and RARβ expression were downregulated in breast cancer samples and that decreased E-cadherin expression is linked to distant metastasis in patients with CRC, we propose that RARβ expression may also be relevant in CRC." (PMID 30944670, 2019). "Moreover, loss of RARβ has been observed in solid tumor cells, including breast cancer." (PMID 19442290, 2009). "The expression of miR-10a and the Retinoic Acid Receptor Beta (RARβ) is significantly increased by retinoic acid (RA) in two breast cancer cell lines, T47D and SK-BR-3." (PMID 38605867, 2024). "Due to their associations with tumor suppression in breast tissue samples, reduced expression of RARβ and miR-10a has been related to breast cancer." (PMID 38605867, 2024). "In Rarb−/− mice (RARβ-null mice), ErbB2-induced mammary tumors display a decrease in the proliferation of neoplastic cells, as well as a diminution of the angiogenetic process, the levels of collagen and the recruitment of inflammatory cells." (PMID 38360674, 2024). "In ErbB2-induced mammary tumors, RARβ was found expressed in a subpopulation of myofibroblasts and its loss dampens their expansion and activity." (PMID 38360674, 2024). "For example, LE135 cotreatment can block the RARb activation, growth inhibition, metabolic and metastasis changes caused by ATRA in breast cancer cells, melanoma cells and pancreatic cancer cells." (PMID 36681687, 2023). "Patients with breast cancer were almost three times more likely to have been exposed to RARB and GSTP1 methylation than controls (OR = 2.81; 95% CI [1.02–8.22]; p = 0.026)." (PMID 37548362, 2023). "One of the first studies that proposed the use of epigenetic biomarkers in plasma to detect breast cancer compared four methylation biomarkers, APC, GSTP1, RASSF1A, and RARB, in primary breast cancer tissue and plasma samples." (PMID 36765815, 2023). "In our sample of Peruvian women, breast cancer patients were almost three times more likely to have been exposed to RARB or GSTP1 methylation than controls." (PMID 37548362, 2023). "Hypermethylation of RARB has been indicated as a possible biomarker for lung cancer, breast cancer, prostate cancer." (PMID 35611845, 2022). "RARβ possesses many functional characteristics of a tumor suppressor in breast cancer cells; however, it promotes the growth and progression of mammary epithelial tumors." (PMID 36175396, 2022). "Combinatorial exposures inhibited breast cancer cell growth and induced death, followed by RARB hypomethylation and numerous increases in RARB, PTEN, and CDKN1A transcript levels." (PMID 35327559, 2022). "In one study, RARβ was induced in 33% of patients with breast cancer when treated with all-trans-retinoic acid for three weeks." (PMID 34579037, 2021). "As retinoids bind to RARα, the compound upregulates the RARβ gene, resulting in the stimulation of a number of cell differentiation and death genes and the inhibition of breast cancer metastasis in vivo." (PMID 34579037, 2021).
breast carcinoma (continued). "If so, it provides mechanistic insights into the prognostic utility of MR in tamoxifen-treated breast cancers and the potential for MR and RARβ to influence breast cancer cell growth through altered energy metabolism." (PMID 33148314, 2020). "RARB was less widely expressed than MR, its detection ranging from 16% RARB positive in HER2 subtype cases to 47% RARB positive in basal-like breast cancers." (PMID 33148314, 2020). "Kaplan-Meier analysis revealed that breast cancers that were characterized by high expression of both MR and RARB represented a subgroup with significantly better survival." (PMID 33148314, 2020). "In the first one, the loss of heterozygosity on chromosome 3p24, including the region coding for RARβ, was reported for breast cancer specimens and normal adjacent tissues." (PMID 32012980, 2020). "The expression of both MR and RARB was higher in normal breast tissues and decreased in breast cancers while the expression of RARG and RARA was high and largely invariant in both sample cohorts." (PMID 33148314, 2020). "Gene sets negatively correlated with MR in breast cancer showed strong enrichment for genes involved in cell cycle regulation while RARB correlated gene sets were strongly enriched with genes involved in cellular metabolism." (PMID 33148314, 2020). "As confirmation of this, the induction of histone re-acetylation at the RARβ promoter in breast cancer cell lines and in tumor xenograft models reactivated the RARβ transcription and obtained significant growth inhibition." (PMID 32012980, 2020). "While RARβ is known to suppress breast cancer through inducing apoptosis and inhibiting metastasis, relatively little is known about the role of MR in breast cancer." (PMID 33148314, 2020). "Nevertheless, TNBC-specific RARβ induction is the consequence of a retinoid-dependent activation of RARα, which is constitutively expressed in all types of breast cancer cells and it is the primary mediator of ATRA activity in mammary tumors." (PMID 33081033, 2020). "The percentage of MR and RARB double-positive detection was highest in normal-like breast cancer (40%), basal-like (35%) and luminal A breast cancer cases (14%)." (PMID 33148314, 2020). "In cancer tissues, there was a lower percentage of MR co-expressed genes shared with RARB (104 genes; 21% of MR co-expressed genes identified in breast cancer)." (PMID 33148314, 2020). "The potential relationship between MR and RARB is also supported by our original observations of a positive expression correlation between MR and RARB in the TCGA breast cancer cohort." (PMID 33148314, 2020). "In support of the findings in the cell line, breast cancers expressing high levels of MR and RARB express higher levels of key pro-glycolysis genes compared with cancers with low MR/RARB expression." (PMID 33148314, 2020). "Subsequently, they correlated the HOXA5 expression with the ATRA treatment only in RARβ positive breast cancer cell lines." (PMID 32012980, 2020). "Although RARβ possesses, in breast cancer cells, many of the functional characteristics of a tumor suppressor, RARβ in the tumor stroma has a dominant role in promoting the growth and progression of mammary epithelial tumors." (PMID 31590252, 2019). "Recent reports have also indicated that RA, and RARβ agonists in particular, inhibits invasion and the migratory potential of breast cancer and endometrial cancer cells." (PMID 30944670, 2019). "The combinatorial exposures synergistically or additively inhibited the growth and induced apoptosis of breast cancer cells, followed by RARB hypomethylation with concomitant multiple increase in RARB, PTEN, and CDKN1A transcript levels." (PMID 30544666, 2018). "In breast cancer patients, the level of dietary methyl donors was correlated with the promoter hypermethylation status of retinoic acid receptor-beta (RARB), BRCA1 and RASSF1A." (PMID 29039788, 2017).